ENSG00000243655 (novel transcript, antisense to MTRNR2L1)
Gene: Long non-coding RNA gene on chromosome 17 (22,524,563 to 22,525,330, reverse strand). Ensembl gene ENSG00000243655.
Gene Ontology:
Molecular function: triplet codon-amino acid adaptor activity
Biological process: translation